ENSG00000285625 (novel protein)
Gene: Protein-coding gene on chromosome 12 (56,714,612 to 56,741,535, reverse strand). Ensembl gene ENSG00000285625.
Genetic constraint (gnomAD): Loss-of-function variants: 11 observed, 12.99 expected, observed/expected ratio (o/e) 0.85, 90% interval 0.53 to 1.4. Missense variants: 98 observed, 131.72 expected, observed/expected ratio (o/e) 0.74, 90% interval 0.63 to 0.88. Synonymous variants: 52 observed, 46.99 expected, observed/expected ratio (o/e) 1.11, 90% interval 0.88 to 1.39.